DANCR (differentiation antagonizing non-protein coding RNA)
Diseases named in the same sentence as DANCR in open-access papers (continued):
Sharing a sentence is not in itself a finding about the gene and the disease.
bladder cancer (continued). "And they found that DANCR was distributed mostly in the cytoplasm and functioned as a miRNA sponge to positively regulate the expression of musashi RNA binding protein 2 (MSI2) through sponging miR-149 and subsequently promoted malignant phenotypes of bladder cancer cells." (PMID 33123287, 2020). "Knockdown of DANCR could inhibit malignant phenotypes and EMT of bladder cancer cells." (PMID 33123287, 2020). "In the present study, we showed that DANCR was significantly up-regulated in bladder cancer tissues compared with corresponding non-tumor tissues in a cohort of 106 bladder cancer patients and its expression was significantly correlated with histological grade and TNM stage." (PMID 30419948, 2018). "Moreover, we found that DANCR and MSI2 were co-localized in bladder cancer cells." (PMID 30419948, 2018). "In this study, we found the expression level of DANCR was significantly up-regulated in bladder cancer tissues compared with corresponding non-tumor tissues and increased DANCR expression was positively correlated with higher histological grade and advanced TNM stage." (PMID 30419948, 2018).
liver cancer (9 papers, 2018 to 2026). An epithelial or non-epithelial malignant neoplasm that arises from the liver. "For example, the SNHG11/miR‐184/AGO2 and DANCR/miR‐222‐3p/ATG7 regulatory loop has been shown to enhance autophagic flux in liver cancer cells, which helps these cells survive under stressful conditions." (PMID 41474641, 2026). "Laboratory studies have found that overexpression of DANCR can promote the proliferation, invasion, and metastasis of liver cancer cells and inhibit apoptosis." (PMID 38802416, 2024). "Research has shown that inhibiting DANCR in mouse liver cancer prolongs tumour formation cycles and reduces the tumour volume, significantly impeding tumour growth." (PMID 38877534, 2024). "LncRNA DANCR was raised in liver cancer tissues and liver cancer cells, and DANCR overexpression facilitated the proliferation and metastasis of liver cancer cells." (PMID 35156514, 2022). "Accumulating investigations have demonstrated that miRNAs and lncRNAs are essential for sustaining CSC properties in liver cancer, like miR-200b, miR-181, miR-1246, lncTCF-7, lnc-DANCR, lnc-PVT1, and so on." (PMID 29888282, 2018). "Additionally, some in vivo experiments indicated that SNHG1, SNHG5, SNHG6, SNHG8, DANCR, SNHG16, and SNHG17 can promote lung metastasis of human liver cancer cells in immunodeficient mice." (PMID 41474641, 2026). "In addition, DANCR can regulate various signaling pathways, such as Wnt/β-catenin, PI3K/AKT, etc46, participating in the occurrence and development of liver cancer." (PMID 38802416, 2024). "Moreover, the interaction of DANCR with heterogeneous nuclear ribonucleoprotein A1 (HNRNPA1) in HepG2 and Huh7 cells enhances HNRNPA1 expression by preventing its degradation and facilitating the EMT, invasion, and migration of liver cancer cells." (PMID 38877534, 2024).
ovarian carcinoma (9 papers, 2018 to 2025). A malignant neoplasm originating from the surface ovarian epithelium. "In recent days, some studies also reported that DANCR played important role in other cancers such as papillary thyroid cancer, esophageal squamous cell carcinoma, ovarian cancer and retinoblastoma." (PMID 33123287, 2020). "Moreover, knockdown of DANCR impaired ovarian cancer tumor growth through inhibition of tumor angiogenesis via up-regulating miR-145." (PMID 36046633, 2022). "DANCR was detected upregulated in ovarian cancer tissues and cell lines." (PMID 34722539, 2021). "Lu et al32 reported that MYC stimulates the transcription of DANCR, and inhibition of DANCR impairs cell proliferation which could be partially rescued by p21 silencing in human ovarian cancer." (PMID 29926523, 2018). "Thus, DANCR might serve as a potential therapeutic target for ovarian cancer treatment." (PMID 34722539, 2021).
non-small cell lung carcinoma (8 papers, 2018 to 2025). A group of at least three distinct histological types of lung cancer, including non-small cell squamous cell carcinoma, adenocarcinoma, and large cell carcinoma. "Moreover, the oncogenic role of DANCR in non-small cell lung cancer has been documented to be associated with its modulation of the tumor suppressor miR-758-3p as a ceRNA26." (PMID 34548487, 2021). "DANCR, identified as a novel lncRNA, has been previously studied for its potential applications in non-small cell lung cancer and bone differentiation." (PMID 38609873, 2024). "The study of Wang revealed that DANCR was markedly upregulated in non-small-cell lung cancer tumor tissues and cell lines compared with related normal controls." (PMID 33123287, 2020). "For examples, DANCR exerted tumor promoter in non-small cell lung cancer by directly targetting miR-758-3p; and DANCR controlled mTOR expression to modulate tumor progression via sponging miR-496." (PMID 30910842, 2019). "The upregulation of DANCR expression was significantly associated with larger tumor size, advanced TNM stage and lymph node metastasis, and also predicted poor prognosis of patients with non-small-cell lung cancer." (PMID 33123287, 2020). "However, the exact mechanisms by which DANCR promotes non-small cell lung cancer (NSCLC) remain elusive." (PMID 33302540, 2020). "In addition, DANCR knockdown suppressed non-small-cell lung cancer cell migration and invasion via inhibition of EMT." (PMID 33123287, 2020). "DANCR could function as a tumor promoter and promote cell proliferation, invasion and migration through directly targeting the tumor suppressor miR-758-3p in non-small-cell lung cancer." (PMID 33123287, 2020). "In addition, Sox4 could bind to the promoter regions of DANCR gene to activate DANCR expression, suggesting a positive feedback loop of DANCR/miR-138/Sox4 in non-small-cell lung cancer." (PMID 33123287, 2020). "Recently, some studies have reported that lncRNA DANCR is up-regulated in various human cancers and its aberrant expression could promote tumor progression by improving cancer cell proliferation and invasion, such as glioma, non-small cell lung cancer, and prostate cancer." (PMID 30910842, 2019).
colon cancer (7 papers, 2018 to 2025). "Given that DANCR is positively associated with colon cancer, to further assess the potential functions of DANCR in cisplatin sensitivity, we transfected DANCR overexpression lentiviral vector into two colon cancer cell lines, HT-29, and SW620." (PMID 32766131, 2020). "DANCR is highly expressed in colon cancer tissues and cell lines, and silencing DANCR inhibits the proliferation, survival, and metastasis of colon cancer via the DANCR/miR-518a-3p/MDM2 axis." (PMID 38002356, 2023). "DANCR expressions were significantly upregulated in 35 colon tumors, consistent with previous reports." (PMID 32766131, 2020). "Our data will potentiate the DANCR interference as a novel antichemoresistance strategy to improve the outcomes of colon cancer." (PMID 32766131, 2020). "In this study, we observed that DANCR was significantly upregulated in colon cancer tissues and cells, consistent with previous reports." (PMID 32766131, 2020). "To investigate the functions of DANCR in chemoresistant colon cancer, we first evaluated DANCR expressions in colon tumors and their adjacent normal tissues." (PMID 32766131, 2020). "This study aims to elucidate the roles of DANCR in regulating cisplatin (CDDP) resistance of colon cancer." (PMID 32766131, 2020). "We found DANCR was significantly upregulated in colon cancer tissues and cells compared with normal colon tissues and cells." (PMID 32766131, 2020). "DANCR was upregulated in cisplatin-resistant colon cancer cells." (PMID 32766131, 2020). "Giving the evidence that DANCR and miR-125b-5p exhibited contrary roles in colon cancer and cisplatin resistance, we asked whether they could oppositely regulate glycolysis of colon cancer cells." (PMID 32766131, 2020). "Expectedly, expressions of DANCR were significantly elevated in colon cancer cells." (PMID 32766131, 2020). "Moreover, by establishing cisplatin-resistant colon cancer cells, we found DANCR was clearly upregulated in CDDP resistant cells." (PMID 32766131, 2020). "Given that DANCR and miR-125b-5p/HK2 inversely regulate cisplatin sensitivity of colon cancer, we examined whether DANCR influenced cisplatin resistance through suppressing the miR-125b-5p/HK2 axis." (PMID 32766131, 2020). "We examined the expressions of DANCR and miR-125b-5p in 35 colon cancer tissues by qRT-PCR, and consistent results demonstrated a significant inverse correlation between DANCR and miR-125b-5p: higher DANCR mRNA levels accompanied with lower miR-125b-5p expressions in colon cancer tissues." (PMID 32766131, 2020). "Together, these results implied that DANCR could directly bind to miR-125b-5p and serve as its ceRNA in colon cancer." (PMID 32766131, 2020). "In this study, we assessed the functions of lnc-DANCR in mediating CDDP resistance in colon cancer." (PMID 32766131, 2020). "On the other way, silencing DANCR dramatically overrode CDDP resistance of colon cancer cells." (PMID 32766131, 2020). "In contrast, DANCR was up-regulated in breast, prostate, liver, and colon cancers." (PMID 30518158, 2018). "DANCR may affect colon cancer cell growth and metastasis through the miR-518a-3p/MDM2 axis." (PMID 38002356, 2023). "Moreover, overexpression of DANCR significantly desensitized colon cancer cells to cisplatin." (PMID 32766131, 2020). "We then asked whether DANCR acts as a ceRNA of miR-125b-5p in colon cancer cells." (PMID 32766131, 2020). "Importantly, silencing endogenous DANCR significantly induced the miR-125b-5p/HK2 axis, resulting in suppression of the glycolysis rate and increase in cisplatin sensitivity of colon cancer cell." (PMID 32766131, 2020). "Moreover, the DANCR expressions were compared in normal colon epithelial cell line, CRL-1790, and five colon cancer cell lines." (PMID 32766131, 2020). "However, the direct miRNA targets of DANCR and the DANCR/miRNA interaction in mediating cisplatin resistance of colon cancer have not been elucidated." (PMID 32766131, 2020).
colon cancer (continued). "We proposed DANCR specifically sponges miR-125b-5p to derepress the expression of HK2, a direct target of miR-125b-5p in colon cancer, presenting the DANCR/miR-125b-5p/HK2-glycolysis axis as a new therapeutic target for overcoming cisplatin resistance of colon cancer." (PMID 32766131, 2020).
cervical cancer (6 papers, 2019 to 2022). A primary or metastatic malignant neoplasm involving the cervix. "In this present study, we provide a novel insight that the activation of the Wnt/β-catenin signalling pathway by DANCR is associated with cervical cancer progression." (PMID 32123519, 2020). "In conclusion, our findings demonstrate that lncRNA DANCR is upregulated in cervical cancer, positively associated with tumor size and FIGO stage, and a prognostic indicator of poor survival of cervical cancer patients." (PMID 32123519, 2020). "Pearson correlation analysis displayed that the expression of FRAT1 and FRAT2 were both positively associated with the expression of DANCR in cervical cancer tissues." (PMID 32123519, 2020). "Therefore, our data demonstrated that DANCR also functions as an oncogene in cervical cancer, further supporting DANCR as a cancer-associated lncRNA." (PMID 32123519, 2020). "DANCR depletion was shown to inhibit the proliferation of cervical cancer cell lines and resulted in decreased tumor size in mouse xenograft models." (PMID 36366537, 2022). "High DANCR expression has similarly been reported in cervical cancer tissue, and depletion of DANCR significantly inhibited proliferation, migration and invasion, whilst siRNA knockdown of TINCR promoted cell growth." (PMID 33427604, 2021). "Increased expression of DANCR is associated with large tumor size, advanced FIGO stage, and poor overall survival of cervical cancer patients." (PMID 32123519, 2020). "Conversely, DANCR knockdown inhibits cervical cancer cell proliferation in vitro and cervical cancer xenograft growth in vivo." (PMID 32123519, 2020). "Functional experiments demonstrated that ectopic expression of DANCR promotes cervical cancer cell proliferation in vitro and cervical cancer xenograft growth in vivo." (PMID 32123519, 2020). "Conversely, DANCR knockdown inhibits cervical cancer cell proliferation in vitro and xenograft growth in vivo." (PMID 32123519, 2020). "In the present study, we determined DANCR expression in cervical cancer tissues and cell lines, analyzed the correlation between DANCR expression and cervical cancer patients’ clinicopathological features, including prognosis." (PMID 32123519, 2020). "In this study, we identified a novel mechanism mediating the oncogenic roles of DANCR in cervical cancer, which is the activation of the Wnt/β-catenin signalling pathway via upregulation of FRAT1 and FRAT2." (PMID 32123519, 2020). "Functional experiments showed that enhanced expression of DANCR promotes cervical cancer cell proliferation in vitro and xenograft growth in vivo." (PMID 32123519, 2020). "DANCR expression was obviously increased in cervical cancer cell lines compared with normal cervical epithelial cell line." (PMID 32123519, 2020). "The roles of DANCR in cervical cancer growth were evaluated by in vitro CCK-8 and EdU assay, and in vivo xenograft assay." (PMID 32123519, 2020). "To determine the functional relevance of DANCR in cervical cancer, we constructed DANCR stably overexpressed and control HeLa cells through transfecting DANCR expressing plasmid (pcDNA3.1-DANCR) or control empty plasmid (pcDNA3.1)." (PMID 32123519, 2020). "High expression of DANCR is positively associated with large tumor size, advanced FIGO stage, and poor overall survival of cervical cancer patients." (PMID 32123519, 2020). "Collectively, these data showed that upregulation of DANCR promotes cervical cancer growth in vitro and in vivo." (PMID 32123519, 2020). "Collectively, these data showed that DANCR is upregulated in cervical cancer tissues and cell lines, and increased expression of DANCR is positively correlated with larger tumor size, advanced FIGO stage, and worse prognosis." (PMID 32123519, 2020). "The results displayed that enhanced expression of DANCR upregulated nuclear β-catenin levels, and while knockdown of DANCR downregulated nuclear β-catenin levels in cervical cancer cells." (PMID 32123519, 2020).
cervical cancer (continued). "Collectively, these data showed that knockdown of DANCR suppresses cervical cancer growth in vitro and in vivo." (PMID 32123519, 2020). "In cervical cancer, however, the expressions, roles, and mechanisms of action of DANCR are still unclear." (PMID 32123519, 2020). "To further validate the functional relevance of DANCR in cervical cancer, we constructed DANCR stably depleted and control C-33A cells via transfecting DANCR specific shRNA (KD-DANCR) or control scrambled shRNA (KD-control)." (PMID 32123519, 2020). "DANCR can modulate the EMT progression by upregulating Rho-associated coiled-coil containing protein kinase 1 (ROCK1) and promote metastasis in cervical cancer." (PMID 31799189, 2019). "High-level DANCR expression has been observed in cervical cancer tissues and derived cell lines (HeLa, SiHa, C-33A, ME-180) and correlates with lower overall survival rates in cervical cancer patients." (PMID 36366537, 2022). "Our findings also implied that DANCR might be a promising prognostic biomarker and therapeutic target for cervical cancer." (PMID 32123519, 2020). "Furthermore, gain-of-function and loss-of-function assays were performed to investigate the biological roles of DANCR in cervical cancer growth." (PMID 32123519, 2020). "Both public available TCGA data and cervical cancer tissues we collected display that the expression of FRAT1 and FRAT2 are positively associated with the expression of DANCR in cervical cancer tissues, supporting the positive regulation of FRAT1 and FRAT2 by DANCR." (PMID 32123519, 2020). "In addition, knockdown of DANCR inhibited cervical cancer cell proliferation, migration, and invasion in vitro, indicating that DANCR functioned as an oncogene in cervical cancer." (PMID 33123287, 2020). "The expressions of DANCR in cervical cancer tissues and cell lines were evaluated using qRT-PCR." (PMID 32123519, 2020). "Moreover, we measured DANCR expression in human normal cervical epithelial cell line HCerEpiC and cervical cancer cell lines HeLa, SiHa, C-33A, and ME-180 via qRT-PCR." (PMID 32123519, 2020). "DANCR promotes cervical cancer growth via activating FRAT1/FRAT2-Wnt/β-catenin signaling pathway." (PMID 32123519, 2020). "DANCR is increased in cervical cancer tissues and cell lines." (PMID 32123519, 2020). "However, the expressions, functions, and mechanisms of action of DANCR in cervical cancer are still unclear." (PMID 32123519, 2020). "Our results imply that DANCR may be a promising prognostic biomarker to evaluate cervical cancer progression and useful therapeutic target for cervical cancer treatment." (PMID 32123519, 2020). "For instance, DANCR competitively sponges the 3′UTR of transforming growth factor beta receptor 1 (TGFBR1) mRNA in cervical cancer cells, which blocks miR-665 from binding to and degrading TGFBR1 and promotes the TGFBR1-mediated oncogenic ERK (extracellular regulated protein kinases)/SMAD pathway." (PMID 31799189, 2019). "Furthermore, we transiently overexpressed DANCR in another cervical cancer cell line SiHa." (PMID 32123519, 2020). "Thus, we used ICG-001 to inhibit Wnt/β-catenin signaling pathway in the functional assays, which led to the abolishment of the pro-proliferation of cervical cancer cells caused by DANCR overexpression and the anti-proliferatory roles of DNACR knockdown in cervical cancer cells." (PMID 32123519, 2020). "Furthermore, we transiently repressed DANCR in another cervical cancer cell line ME-180." (PMID 32123519, 2020). "We demonstrated that DANCR, which is an oncogenic lncRNA in cervical cancer through activating the Wnt/β-catenin signaling pathway, might be a promising prognostic biomarker and therapeutic target for cervical cancer." (PMID 32123519, 2020). "Our findings suggest DANCR as an oncogenic lncRNA in cervical cancer through activating the Wnt/β-catenin signaling pathway, and imply that DANCR may be a promising prognostic biomarker and therapeutic target for cervical cancer." (PMID 32123519, 2020).
cervical cancer (continued). "Our results displayed that enhanced expression of DANCR upregulated the mRNA and protein expression levels of C-myc and Cyclin D1, and while knockdown of DANCR downregulated the mRNA and protein expression levels of C-myc and Cyclin D1 in cervical cancer cells." (PMID 32123519, 2020). "Several recent studies have reported the role of DANCR in cervical cancer associated with certain miRNAs, however whether DANCR also affects the Wnt/β-catenin signalling pathway in cervical cancer has not been revealed." (PMID 32123519, 2020). "Our results displayed that enhanced expression of DANCR upregulated the mRNA and protein expression levels of FRAT1 and FRAT2, and while knockdown of DANCR downregulated the mRNA and protein expression levels of FRAT1 and FRAT2 in cervical cancer cells." (PMID 32123519, 2020). "In this study, we identified DANCR is upregulated in cervical cancer tissues and cell lines compared with adjacent noncancerous cervix tissues and normal cervical epithelial cell line, respectively." (PMID 32123519, 2020). "Our results displayed that DANCR expression was markedly increased in cervical cancer tissues compared with adjacent noncancerous cervix tissues." (PMID 32123519, 2020).